ENSG00000239096
Synonyms: LOC124906348
Gene: Small nucleolar RNA gene on chromosome 3 (179,614,775 to 179,614,878, reverse strand). Ensembl gene ENSG00000239096.
Gene Ontology:
Biological process: RNA processing
Cellular component: nucleolus
Homologues: Paralogues in human: SNORD13P1 (85% identical), SNORD13 (83% identical), SNORD13D (83% identical), SNORD13E (79% identical), SNORD13P3 (79% identical).